APC (APC regulator of Wnt signaling pathway)
Diseases named in the same sentence as APC in open-access papers (continued):
Sharing a sentence is not in itself a finding about the gene and the disease.
colorectal cancer (continued). "Second, clinico-pathological features suggested many of the APC-mutated CACs were actually sporadic colorectal cancer whereas RNF43-mutated CACs did not have this tendency." (PMID 29416670, 2018). "APC mutations remain constantly represented in the progression from adenomas to colorectal cancers, while CTNNB1 mutations become less frequent in the tumor spectrum from small adenomas to colorectal cancers." (PMID 29652830, 2018). "When APC and CTNNB1 mutations were compared, there was evidence for selection of CTNNB1 mutations over common APC mutations in each of liver cancer, uterine carcinoma, prostate cancer and colorectal cancer." (PMID 29748584, 2018). "These include APC for colorectal cancer, with a large number of studies, and SHOX3, for which a recent meta-analysis suggests that it could have an important role in the diagnosis of lung cancer." (PMID 29061138, 2017). "In colorectal cancer, genetic mutation of Adenomatous Polyposis Coli (APC) in the Wnt-signaling cascade is a major contributing factor for familial colorectal cancers, but it is typically not the primary mechanism associated with breast cancer." (PMID 28402277, 2017). "Improved understanding of both the genetics and patho-biology of APC may, in time, culminate in preventative or therapeutic strategies specifically targeted at reducing the burden of colorectal cancer." (PMID 28423518, 2017). "Colorectal cancer (CRC) is a disease that originates from the epithelial cells lining the rectum or the colon and is frequently associated with genetic alterations in the K-ras and β-catenin oncogenes as well as APC and Bax tumor suppressors." (PMID 28099904, 2017). "A recent large scale meta-analysis showed that common genetic variants in APC and MLH1 genes, two genes known to have high-penetrance mutations contributing to familial colorectal cancer, had strong cumulative epidemiological evidence for a significant association with colorectal cancer risk." (PMID 29088836, 2017). "Loss of the negative Wnt pathway regulator APC takes place in the majority of colorectal cancers such as FAP." (PMID 28331559, 2017). "Another experimental study demonstrated that L1 can be inserted in the APC tumor suppressor gene, which may be correlated with initiation of colorectal cancer." (PMID 28166262, 2017). "Furthermore, a chemical compound targeting PrxII inhibits the expansion of APC-mutant colorectal cancer cells in vitro and in vivo tumor xenografts." (PMID 28659575, 2017). "Reduced sensitivity to 5-FU was also demonstrated in APC mutant colorectal cancer (CRC) cell lines." (PMID 27729614, 2016). "Moreover, loss of heterozygosity and promoter hypermethylation of APC has been observed in FAP and colorectal cancer." (PMID 27000756, 2016). "Aberrant epigenetic modification of APC was also observed in colorectal cancer as well as in NSCLC." (PMID 26862903, 2016).
colorectal cancer (continued). "Hence, deletion of APC C-terminal domains is expected to contribute to the chromosomal instability observed in many colorectal cancers." (PMID 27047543, 2016). "Of note, unlike colorectal cancer, breast cancer cells exhibit infrequent genetic mutations of APC or β-catenin/CTNNB1 (refs 49, 50), which implies that additional regulatory mechanisms of Wnt signalling exist." (PMID 26843124, 2016). "The significance of this finding is not clear since RNF43 mutations and APC mutations in colorectal cancer are mutually exclusive and the localization of RNF43 on the inner layer of the nuclear membrane has not been demonstrated." (PMID 27338477, 2016). "APC is a well-known tumour suppressor that is frequently inactivated in colorectal cancer." (PMID 27302369, 2016). "The majority of our colorectal carcinomas with LOH for APC gene are copy number neutral." (PMID 26970738, 2016). "In particular, recent published works point out at other genes implied in colorectal cancer pathogenesis (APC, MUTYH, STK11 and BRCA1/2) as explanations of familial colorectal cancer syndromes in patients who do not present mutations in standard MMR protein gene system." (PMID 26485756, 2015). "Notably, MLH1 and MGMT have been previously associated with two distinct methylation landscapes in colorectal cancer that exhibited important differences in terms of KRAS and APC mutation frequency." (PMID 25960768, 2015). "In addition, we also investigated critical molecular events such as APC, KRAS, BRAF and PIK3CA mutations and MSI, all of which have been associated with colorectal cancer prognosis to justify the prognostic role of NEAT1." (PMID 26314847, 2015). "Unfortunately, only a minority of colorectal cancers (23%) falls into the wild-type APC group." (PMID 26311743, 2015). "The genes mostly implicated in the inheritance of adenomatous polyposis, a condition that leads to colorectal cancer, are adenomatous polyposis coli (APC) involved in FAP (OMIM #175100) and mutY Homolog (MUTYH) involved in MUTYH-associated polyposis (MAP) (OMIM#608456)." (PMID 26511139, 2015). "Besides the APC gene, which occurs in over two-thirds of colorectal cancer, WNT2 and MACF1 also impact the Wnt pathway, while RASA1 is in the RAS pathway." (PMID 25974029, 2015). "However, this is only partly satisfying because the ectopic expression of Axin or Axin2 in colorectal cancer cell lines expressing APC that is truncated before the SAMP repeats results in efficient β-catenin destruction." (PMID 24722208, 2014). "Somatic APC defects are found in about 80% of colorectal cancers (CRCs) and adenomas." (PMID 24763434, 2014). "APC inactivation is also seen in 80% of sporadic colorectal adenomas and colorectal cancers (CRCs)." (PMID 24763434, 2014). "Mutations in the WNT-pathway regulator ADENOMATOUS POLYPOSIS COLI (APC) promote aberrant activation of the WNT pathway that is responsible for APC-associated diseases such as Familial Adenomatous Polyposis (FAP) and 85% of spontaneous colorectal cancers (CRC)." (PMID 25003333, 2014). "The role of rare nonsynonymous missense variants of the APC gene in colorectal cancer predisposition is not clear." (PMID 24790607, 2014). "However, different APC truncations freguently happen in colorectal cancer, which usually lead to different molecular consequences on β-catenin regulation." (PMID 24977433, 2014).
colorectal cancer (continued). "Examples of other hypermethylated genes used to predict poor clinical prognosis include CDKN2A in colorectal cancer, RASSF1A and APC in breast cancer, the apoptosis-associated gene DAPK1 in lung and head and neck cancers, and CDKN2A, RASSF1A, cadherin 13 (CDH13) and APC in stage I NSCLC." (PMID 25473433, 2014). "Germline APC mutation is not a common cause of colorectal cancer, but somatic mutations of the APC gene occur in about 80% of sporadic colon cancers." (PMID 24790607, 2014). "In these signaling pathways, Ras, Myc and APC are involved in colorectal carcinoma maintenance." (PMID 24857950, 2014). "Additional support for our observation that APC controls cell-cell interactions is provided by studies in APC-mutant colorectal cancer cells in which APC re-introduction induced β-catenin/E-cadherin localization at the adherens junction and promoted a more epithelial, less motile phenotype." (PMID 23302090, 2013). "This region contains an element that regulates the expression of an upstream candidate tumor suppressor, PPM1L, thus providing a novel mechanism for colorectal tumorigenesis in APC mutation-negative familial colorectal cancer." (PMID 23258604, 2013). "For locally advanced or metastatic disease, chemotherapeutic agents used in the treatment of colorectal cancer may be effective in ACC of the pancreas due to the genetic alteration in the APC/β-catenin pathway noted in acinar cells of the pancreas." (PMID 23426888, 2013). "Indeed, a Sleeping Beauty transposon mutagenesis screen using a mouse model of colorectal cancer found specific mutations in MCC and APC at a 1:9 ratio." (PMID 23540693, 2013). "In colorectal cancer cells, the destruction complex member APC is often truncated." (PMID 24086117, 2013). "Among them, APC and FBXW7 were reported as two mutated gene ‘mountains’ in colorectal carcinomas." (PMID 23301059, 2013). "Thus, truncated APC is an essential component of colorectal cancer cells, required for cell proliferation, possibly by adjusting β-catenin signalling to the “just right” level." (PMID 22509309, 2012). "In the next step, we asked whether a reduction of the APC level in colorectal carcinoma cells would also inhibit the formation of tumours in nude mice." (PMID 22509309, 2012). "Unlike colorectal cancer where mutation is the primary mechanism for APC loss, APC expression is frequently down-regulated through transcriptional silencing via gene promoter methylation in breast cancer." (PMID 22216254, 2011). "Secondly, we analyzed 56 cases of colorectal cancer known to carry the APC I1307K mutation, together with 32 mutation carriers without colorectal cancer." (PMID 20470408, 2010). "Since KLF5 has been shown to mediate the function of both APC and RAS, and mutations in APC and KRAS are common events in colorectal cancer, we examined the role of KLF5 in mediating intestinal tumor formation in mice compound for ApcMin and intestine-specific KRASV12 mutations in the current study." (PMID 20298593, 2010). "The human 5q22.2 and 18q21.1-q21.2 regions are both constantly disrupted in human CRCs, and encode bona fide CRC driver genes (e.g., APC, SMAD4) as well as genes whose role in cancer etiology remains unclear (e.g., mutated in colorectal cancer or MCC)." (PMID 20707908, 2010). "Besides the bona fide tumor suppressor APC, 5q22.2 also encodes the gene MCC (mutated in colorectal cancer)." (PMID 20707908, 2010). "The APC gene is also inactivated in greater than 80% of sporadic colorectal cancer." (PMID 20298593, 2010).
colorectal cancer (continued). "Currently, patients with multiple colorectal adenomas, no APC gene mutation or HNPCC related colorectal cancer and no MMR gene mutation are recommended to undergo testing for germline mutations in MUTYH." (PMID 19338676, 2009). "Unlike colorectal cancer, evidence for genetic alterations of Wnt pathway components in breast cancer, such as adenomatous polyposis coli (APC) mutations, is rare." (PMID 19570204, 2009). "The APC protein plays a pivotal role in WNT signal transduction, has been suggested to have important functions in cell migration and mitosis, and APC mutation is a crucial early event in the development of most colorectal cancers." (PMID 16423286, 2006). "The current data on Wnt antagonists in colorectal cancer indicate that their methylation and inactivation may occur before APC action is lost, and two independent studies in mice are consistent with this." (PMID 16523202, 2006). "This has previously been demonstrated for APC in colorectal cancer samples by Esteller et. al." (PMID 15476557, 2004). "Unlike the frequent APC mutations in colorectal cancer, APC mutations are rare in lung cancer." (PMID 40818609, 2025). "However, a germline mutation in APC is not 1:1 related to colorectal cancer (CRC), and only some patients respond to immune checkpoint inhibitors." (PMID 41516021, 2025). "In colorectal cancer, increased protein stability of the WNT effector β-Catenin is critical for tumorigenesis and mediated either by loss of function mutations and truncations within the APC gene or via mutations of the degron motive within CTNNB1, the gene encoding β-Catenin." (PMID 39443725, 2024). "In many colorectal cancers, β-catenin is not degraded properly because of mutation of the tumor suppressor APC, and it then facilitates transcription of cell proliferation genes or interacts with cell structural proteins and contributes to cell adhesion and migration." (PMID 39594797, 2024). "Understanding the mechanistic link between APC inactivation and alterations in lipid metabolism may foster identification of new therapeutic targets to enable development of more efficacious strategies for prevention and/or treatment of colorectal cancer." (PMID 38590663, 2024). "The frequency of cancer driver mutations among tissues is non-uniform: for instance, mutations in APC are particularly frequent in colorectal cancer, and 99% of chronic myeloid leukemia patients harbor the driver BCR-ABL1 fusion mutation, which is rarely found in solid tumors." (PMID 38247798, 2024). "However, APC, the tumor suppressor gene most frequently mutated in colorectal cancer, was not altered in any of the PMP models as previously reported." (PMID 39018564, 2024). "As such, the common APC mutation in colorectal cancer is not detected in MC38, nor in CT26 cells." (PMID 38254785, 2024). "While genes like KRAS, APC, and PIK3CA maintain mutation frequencies relatively consistent with MSS colorectal cancer, the most significant observation is the markedly higher mutation frequency of DNA mismatch repair (MMR)‐related genes in MSI‐H colorectal cancer compared to MSS colorectal cancer." (PMID 38746969, 2024). "Therefore, we explored whether collective cell migration was compromised in APC-m4 colorectal cancer cells." (PMID 37128612, 2023).
colorectal cancer (continued). "In itself, the APC I1307K mutation is not sufficient to cause cancer, but rather increases susceptibility of the APC gene to additional changes that may lead to colorectal cancer." (PMID 36611031, 2023). "Thus, it is worth to verify experimentally whether the IFNγ/IFNGR2/APC/TCF4/GPX4 axis exists in colorectal cancer cells that, once taking on actions, triggers ferroptosis in colorectal CSCs." (PMID 37671945, 2023). "Similarly, PKA activation in APC-mutant colorectal cancer could exert important effects on CTNNB1 via inhibition of GSK3." (PMID 36692000, 2023). "Colorectum cancer is likely to require constitutive Wnt activation through mutation with inactivation of BMP/TGFβ signaling and Ras pathway activation, and it has recurrently mutated non-coding elements including APC and SMAD4 splice regions and ST6GALNAC1 distal promoter." (PMID 38068961, 2023). "Interestingly, the analysis of immune cell populations suggests a propensity for neutrophil recruitment to BRAF/KRAS mutant CRLM in the absence of APC mutations, corroborating observations from serrated colorectal cancer murine models in human patients." (PMID 37057593, 2023). "Colorectal cancers have the highest number of Wnt signaling mutations, and nearly 85% of colorectal cancers have a loss-of-function mutation in APC, while 50% of tumors without an APC mutation have an activating mutation in β-catenin." (PMID 35163279, 2022). "In addition, we assessed the survival of synchronised/serum-starved human APC-mutated colorectal cancer cell line DLD-1 versus CCD-841 normal colon cells after treatment with ten increasing doses of 5-FU ± anti-miR-135 by SRB colorimetric assay." (PMID 35046388, 2022). "Likewise, aberrant increases of APC10 and APC11 proteins, which are two subunits of the APC/C encoded by ANAPC10 and ANAPC11 genes, have been recently evidenced in non-small cell lung and colorectal cancer tissues; interestingly, inhibitors of APC/C activity are currently under investigation." (PMID 33585202, 2020). "However, functional SMAD4 inactivation alone is not sufficient for tumour initiation, but it is thought to promote tumour progression in conjunction with additional alterations, e.g. activating KRAS (pancreatic duct adenocarcinoma) or inactivating APC alterations (colorectal cancer)." (PMID 32198650, 2020). "In vitro activation of the Wnt signalling pathway mediates chemoradiotherapy resistance in colorectal cancer cell lines, however our dataset did not demonstrate any dynamic alteration in frequency of APC mutations over the course of NACRT among all patients or as a function of TRG response." (PMID 32640573, 2020). "On the other hand, the ApcMin/+ model carries a germline mutation in the APC gene that results in familial adenomatous polyposis (FAP), an autosomal dominant disorder characterized by the presence of multiple adenomatous polyps with a high likelihood of developing colorectal carcinomas." (PMID 32340123, 2020).